IFNB1 (interferon beta 1)
Diseases named in the same sentence as IFNB1 in open-access papers (continued):
Sharing a sentence is not in itself a finding about the gene and the disease.
multiple sclerosis (288 papers, 2006 to 2025). A progressive autoimmune disorder affecting the central nervous system resulting in demyelination. "IL1B, P2RX7, IFNB1, IFNB1, TNF, and CASP1 enhance the network connectivity between multiple sclerosis (MS) complex genomes associated with COVID-19 and NOD-like receptor (NLR) signaling." (PMID 36483456, 2022). "Pegylated forms of IFNα and IFNβ have been used in the setting of Hepatitis B and C (Pegylated Alfa-2a/Pegasys, Genentench Inc.)and in Multiple Sclerosis (Pegylated interferon beta-1a/Plegridy, Biogen Canada)." (PMID 33953842, 2021). "IFN specialization is also evident in the clinical use of recombinant subtypes, with IFNB1 being the most effective for the treatment of multiple sclerosis, whereas IFNA2 preparations are preferred for the treatment of chronic viral infections and some malignancies." (PMID 35217532, 2022). "Six and half years later, she was diagnosed with multiple sclerosis and was commenced on interferon beta-1 alpha, with no recurrent episode of TTP." (PMID 28791286, 2017).
COVID-19 (243 papers, 2020 to 2026). A disease caused by infection with severe acute respiratory syndrome coronavirus 2. "IFNB1 is found to be associated with an increased neutrophil to lymphocyte ratio, a marker for COVID-19 late severe outcomes." (PMID 38077337, 2023). "Twenty-one (38.9%) patients received remdesivir, 20 (37.0%) received interferon beta-1b and 10 (18.5%) received dexamethasone to treat COVID-19." (PMID 36949763, 2023). "Thus, our study suggests IL6/IL6R signaling as a plausible ‘downstream’ therapeutic target in IFNB1-overexpressing patients with COVID-19, which should be investigated in future clinical trials." (PMID 37217661, 2023). "In contrast, IFNB1 and IFNA6 were significantly correlated with the neutrophil/lymphocyte ratio (N/L ratio), a marker of severe COVID-19 pathology." (PMID 35217532, 2022). "The interferon-related genes IFNB1, ISG15, and IFIT1 were also activated in COVID-19 patients, and GO analysis showed that HERV-K (HML-2) can regulate the secretion of interferon." (PMID 35632738, 2022). "At 6 days post infection, Ifnb1 expression was significantly attenuated by 4-OI, providing further indication that suppressing type I IFN signaling is critical in reducing TF-mediated coagulopathy in COVID-19." (PMID 37316487, 2023). "The best predictive models for mortality comprised IFNB1 or age, viral ORF7a and ACE2 receptor transcripts, whereas comparison with pre-vaccine fatal COVID-19 signatures uncovered a unique IRF3 low/IRF7 high immune signature in post-vaccine fatal COVID-19 outbreaks." (PMID 37217661, 2023). "We did not detect changes in IFNL2,3, IFNL1, and IFNB1 expression, in agreement with reports of low IFN induction by SARS-CoV-2 infection and the role of several SARS-CoV-2 proteins as IFN-antagonists to limit antiviral response." (PMID 34446714, 2021). "Additionally, we identified that levels of IFNβ in the plasma of COVID-19 (+) patients with T2D were significantly decreased compared to non-T2D COVID-19 (+) patients, and that coronavirus-infected T2D human and diabetic (DIO) murine Mφs expressed less IFNB1 than their non-T2D infected controls." (PMID 34479991, 2021).
melanoma (136 papers, 2007 to 2026). A malignant, usually aggressive tumor composed of atypical, neoplastic melanocytes. "Another strategy for the treatment of melanoma is based on the delivery of the IFNB1 into the tumor." (PMID 41373826, 2025). "Treatment with SB02024 or SAR405 also significantly increased IFNB1 expression in human melanoma Me30966 cells." (PMID 38506049, 2024). "As previously shown in other cell types, the d106S infection resulted in a minor type I IFN response within the melanoma cells, as shown by IFN-β(IFNb1) expression." (PMID 36881506, 2023). "TCGA database of SKCM also showed a strong positive correlation between expressions of SMPD3 and IFNB1 in melanoma tissues, suggesting that TEVs increased IFN-β expression in human melanoma tissues." (PMID 34751648, 2021). "TRIM16 knockdown strongly increased cell migration in normal human epidermal melanocytes, while TRIM16 overexpression reduced cell migration and proliferation of melanoma cells in an interferon beta 1 (IFNβ1)-dependent manner." (PMID 25333256, 2014). "The regulatory inflammatory cytokine, interferon beta 1 (IFNβ1) has been used in the therapy of melanoma." (PMID 25333256, 2014). "Delivering the IFNB1 into melanoma cells with its defective expression may increase these cells’ susceptibility to IFNB1, which exerts a dose-dependent anti-proliferative and apoptotic effect on melanoma cells." (PMID 41373826, 2025). "In Ifnb1−/− mice after B16F10 melanoma implantation, enhanced tumor growth, angiogenesis, and metastasis were observed and accompanied by higher levels of TANs compared with tumors developed in Ifnb1+/+ mice." (PMID 36555469, 2022). "Importantly, and emphasizing acute (fast‐acting) roles of IFN responses, we validated an over 1,000‐fold induction of IFNB1 4h after treatment in HLEC with similar kinetics than for melanoma cells." (PMID 34762341, 2021). "NOS1 overexpression significantly inhibited IFNB1 and IRF7 transcription in A375 melanoma cells in response to Poly(I:C) stimulation, and this inhibition was reversed by NOS1-knockout." (PMID 41535256, 2026). "In this study, we found that a small amount of IRF7 in resting tumor cells can be modified by NOS1-mediated S-nitrosylation, thereby inhibiting IRF7-mediated transcription of IFNB1, resulting in impaired activation of the type I IFN signaling in melanoma cells." (PMID 41535256, 2026). "Moreover, we found that patients with melanoma showed strong positive correlation between FOXP3 and IFNB1 expression." (PMID 34751648, 2021). "The constitutive lack of endogenous IFN-β (Ifnb1−/− mice) as well as the lack of type I IFN signaling (Ifnar1−/− mice) leads to increased growth of different types of tumors (B16F10 melanoma, 4T1 mammary carcinoma, LLC carcinoma, and MCA205 fibrosarcoma) and enhanced metastatic processes." (PMID 28066438, 2016).
influenza (116 papers, 2010 to 2026). An acute viral infection of the respiratory tract, occurring in isolated cases, in epidemics, or in pandemics; it is caused by serologically different strains of viruses (influenzaviruses) designated A, B, and C, has a 3-day incubation period, and usually lasts for 3 to 10 days. "We next assessed expression levels of various cytokines and chemokines (i.e., IFNB1, IFNL1, IFNL2/3, IFIT1, IFIT3, OAS1, MX1, IL‐6, CXCL10, and IFITM1) which were triggered by influenza and OC43 virus infections alone or together by qPCR." (PMID 38556468, 2024). "Reduction of STING gene expression or other anti-viral factors (e.g. IFNB1, MX1, ISG15) by apocynin, may in part, explain the slight increase in influenza gene transcription following apocynin treatment." (PMID 30341336, 2018).
breast cancer (75 papers, 2009 to 2025). A primary or metastatic malignant neoplasm involving the breast. "In a panel of human breast cancer cell lines, PARP7i similarly showed greater-than-additive synergy with RT in driving IFNB1 expression in most models tested, underscoring its broad potential as an amplifier of RT-induced ISG responses." (PMID 41282221, 2025). "The type III IFN genes induced in MCF-7 cells are all expressed in a number of breast cancers and of the type I IFNs, only IFNB1 was found in MCF-7 cells and it was also the most frequently expressed type I gene in breast cancers." (PMID 33770100, 2021). "We may consider interferon beta 1 (IFNβ1), which breast cancer cells secrete to reprogram stromal fibroblasts and foster tumor expansion." (PMID 38250812, 2023). "Interestingly, the gene sets of ISs (AIM2, IFIH1 and TLR3), ISs and IFN-β (IFNB1), and all (ISs, IFNB1, IRF7 and TRAIL) showed strong correlations in ER-negative and lymph node positive or basal-like breast cancer patient survival." (PMID 27077807, 2016).
ZIKV infection (70 papers, 2017 to 2026). "Future transcriptomic studies defining ATF3 genomic occupancy during ZIKV infection will elucidate how this stress-induced transcription factor differentially directs the expression of IFNB1 and other ISGs." (PMID 39212382, 2024). "Top selected ZIKV infection-associated genes from RPE cells are shown in a heatmap that includes multiple immune response genes, such as CCL5, CXCL11, CXCL1, IFNB1, IL6 and TNFSF10." (PMID 30046058, 2018). "Minimal DC activation and antagonism of type I interferon (IFN) translation was observed during ZIKV infection, despite strong induction of IFNB1 transcription and translation of other antiviral effector proteins." (PMID 28152048, 2017). "This was in contrast to RIG-I agonist treatment, which induced translation of both type I and III IFN proteins, despite similar levels of IFNB1 transcription as observed during ZIKV infection." (PMID 28152048, 2017). "Hence, we examined the ISGs transcript levels for DDX58, IFIT1, ISG15, and IFNB1, and analyzed the transcript levels of inflammatory cytokines including TNF-α and IL-6 that are associated with severe symptoms during ZIKV infection." (PMID 34745057, 2021). "To determine if a similar phenomenon occurs during ZIKV infection of human DCs, we compared IFNB1 transcript levels after performing cDNA synthesis with random hexamers, which will prime all RNA species, or Olido(dT), which will only prime polyadenylated transcripts." (PMID 28152048, 2017). "We found that although ZIKV infection induced phosphorylation of IRF3 in SC, this was dramatically diminished by R428 treatment, suggesting that IFNB1 and IFNL1 transcription in SC is responsive to ZIKV genome replication and not directly modulated by Axl-IFNAR signaling." (PMID 31311882, 2019). "Here again, CC071 MEFs showed a delayed expression of Ifnb1 after both stimulations by comparison with B6 and CC001 MEFs, indicating that the defect in IFN-I genes expression in CC071 MEFs was not specific to ZIKV infection." (PMID 37733807, 2023).
asthma (65 papers, 2010 to 2025). "Both BCL-10 and IFNB1 are known to be associated with asthma status." (PMID 32900903, 2020). "Similarly, asthma was associated with lower fold increases in RV-induced IFNB1 mRNA (p = 0.01) and IL28 mRNA (p = 0.009)." (PMID 24219422, 2013). "We did not observe any significantly differential expression of type III interferon genes (IL28A, IL28B and IL29), or type I interferon gene IFNB1 related to asthma, although they showed robust responses to RV-A16." (PMID 25706956, 2015). "Interferon-β1 (IFNB1) was significantly up-regulated in all cultures of all groups except for the lower airways of asthma patients." (PMID 24475887, 2014). "Overall, RV replication was positively related to CXCL10 secretion and induction of IFNB1 and IL28 mRNA, but the positive relationship between RV RNA and CXCL10 secretion was stronger in normal subjects than in subjects with asthma." (PMID 24219422, 2013). "However, the induction of several interferon-related genes (IRF3, IFNAR1, IFNB1, IFNGR1, IL28B) was impaired in patients with asthma." (PMID 24475887, 2014). "Among the genes that were induced in all subjects except for patients with asthma were interferon involved genes (IL28B, IFNAR1), CCL22, and FOSL1 with respect to the upper airways, and several interferon involved genes (IRF3, IFNAR1, IFNB1, IFNGR1, IL28B) in the lower airways." (PMID 24475887, 2014). "Overall, there was a positive correlation between RV RNA levels and induction of both IFNB1 mRNA (r = 0.69, p < 0.001) and IL28 mRNA (r = 0.71, p < 0.001), and this relationship was not affected by asthma status (interaction terms p = 0.36 for IFNB1 and p = 0.54 for IL28)." (PMID 24219422, 2013).
glioma (56 papers, 2008 to 2025). A benign or malignant brain and spinal cord tumor that arises from glial cells (astrocytes, oligodendrocytes, ependymal cells). "The study identified eight co-downregulated miRNAs, three co-upregulated miRNAs, and seven genes associated with overall glioma survival, namely, KRAS, IFNB1, ALCAM, ERBB2, STAT3, FOSL1, and EN2." (PMID 36061185, 2022). "In addition, IFNB1 in vitro treatment reduced levels of miR-21, one of the most commonly upregulated miRNAs in glioma, via STAT3 activation." (PMID 23468990, 2013). "As compared to the normal brain tissues, the genes with decreased copy numbers, such as IFNA1, IFNB1, and IFNG, had lower expression levels in glioma." (PMID 36428756, 2022). "Levels of the Ifnb1, Cxcl9, Cxcl10 and TNF-α mRNAs in glioma tissues from different treatment groups were determined using qRT-PCR to evaluate the activation of STING signaling." (PMID 35386310, 2022).
autoimmune disease (53 papers, 2007 to 2026). A disorder resulting from loss of function or tissue destruction of an organ or multiple organs, arising from humoral or cellular immune responses of the individual to their own tissue constituents. "Understanding the MAPK15 role in regulating IFNB1 and inflammation helps clarify how this pathway can be targeted to manage inflammatory and autoimmune disorders." (PMID 40507959, 2025).
hepatoma (44 papers, 2008 to 2025). "Supporting our findings, PTP4A1 has previously been shown to protect RIG-I from SHP2/PTPN11-dependent degradation, and knock-out of PTP4A1 reduced RIG-I levels and abolished RIG-I-dependent upregulation of IFNB1 in HepG2 hepatocellular carcinoma cells." (PMID 39995872, 2025). "NFATc3 binds to the promoter regions of IFNL1 and IFNB1 to activate their transcription in a synergistic manner with the RIG-I pathway, which can inhibit hepatitis B virus replication and hepatocellular carcinoma tumorigenesis." (PMID 39822413, 2024).
lung carcinoma (36 papers, 2009 to 2026). "In the human lung cancer cells, from which the CM was derived for the ex vivo culture, TNF, IL6 and IFNB1 were upregulated upon Snail OE, while IFNG was undetectable." (PMID 30190790, 2018).
Autoimmunity (33 papers, 2008 to 2026). The occurrence of an immune reaction against the organism's own cells or tissues. "Another UR encodes immunity-related GTPase family M protein 1 (Irgm1), which modulates resistance to pathogens and can contribute to autoimmunity; similarly, the UR interferon beta 1 (IFNB1) is crucial for the antiviral immune response but can also contribute to autoimmunity." (PMID 34768809, 2021).
HCMV infection (33 papers, 2007 to 2026). "Taken together, these data suggest that the cGAS/STING activity promotes VPA-responsive IFNB1 and viral IE gene expression during HCMV infection of incompletely differentiated myeloid cells." (PMID 38932169, 2024). "Compared to non-silencing (ns) control siRNA treated cultures, significantly less IFNB1 mRNA accumulated in response to HCMV infection upon HMGB2-depletion." (PMID 31841110, 2019). "In STING KD HFF cells, HCMV infection-induced expression of IFNB1 transcripts was significantly reduced by 2.8-fold compared with control cells (compare lane 4 with 2)." (PMID 29018427, 2017). "In HFF cells transduced with pLHCX-STING-myc retroviral vector, HCMV infection-induced IFNB1 expression was further induced 2.1-fold compared with control cells (compare lane 4 with 2)." (PMID 29018427, 2017). "The residual expression of IFNB1 transcripts induced by HCMV infection in STING KD cells was possibly mediated by the remaining STING protein and/or other innate immune signaling pathways such as Toll-like receptor (TLR) 2 and 9 (compare lane 4 with 1)." (PMID 29018427, 2017). "Treatment with Ru.521 did not affect cell viability, but it inhibited the induction of IFNB1 transcripts following infection with AD169, confirming that cGAS activity is required for the IFN-I response to HCMV infection in THP1 cells." (PMID 38932169, 2024). "We observed that depletion of ATRX resulted in a suppressed innate immune response to HCMV infection, as detected by reduced phosphorylation of IRF3 and decreased IFNB1 transcription." (PMID 35939517, 2022). "We found that the knockdown of CD147 expression in HFF cells decreased the activation of IFNB1 and interferon-stimulated ISG15 gene expression induced by HCMV infection, as well as expression of the NF-κB downstream genes IL-6 and TNF-α." (PMID 29194430, 2017). "Upon progression of HCMV infection, IFNB1 but not IFNL1 expression was inhibited, and ISG expression was shut off." (PMID 38409141, 2024). "Surprisingly, accumulation of IFNB1 mRNA and a representative ISG-encoded polypeptide (IFIT2 protein) were significantly reduced in response to HCMV infection when cells were treated with TIF-IA siRNA compared to non-silencing siRNA." (PMID 31841110, 2019). "Taken together, these data suggest that the role in promoting IFNB1 and VPA-responsive IE gene expression downstream of cGAS/STING during HCMV infection is specific to TBK1 and that IKKε may instead restrict viral gene expression during HCMV infection of incompletely differentiated myeloid cells." (PMID 38932169, 2024). "Moreover, in bystander cells, IFNB1 expression was associated with viral IE gene transcription, whereas in productively infected cells expression of the highly anti-viral IFNB1, but not IFNL1, was counter-regulated upon progression of HCMV infection." (PMID 38409141, 2024).
depression (31 papers, 2012 to 2025). "Thus, all interferon beta drugs and peginterferon beta-1a should be used with caution in MS patients with a history of depressive disorder." (PMID 31202258, 2019). "By inhibiting the cGAS-STING pathway, exercise reduces the expression of interferon beta-1 (IFNβ1) and other pro-inflammatory cytokines IL-6 and TNF-α, thereby decreasing the inflammatory response, improving mitochondrial function, and alleviating depression." (PMID 40699781, 2025).
Sepsis (30 papers, 2011 to 2025). Sepsis is defined as life-threatening organ dysfunction caused by a dysregulated host response to infection. "The MS-IFNB1 Z scores were higher than the PBMC-derived Z scores, but IFNW1, IFNA2, and IFNB1 were still highly significant (Z > 3) for all SLE WB, PBMC, and affected tissues, the control dermatomyositis dataset, but not the sepsis dataset." (PMID 31044165, 2019).
glioblastoma (28 papers, 2005 to 2025). The most malignant astrocytic tumor (WHO grade IV). "In terms of interferons and receptors, IFNGR2 conferred sensitivity to T-cell mediated cytotoxic activity and enhanced the anti-tumor effectiveness of CD8+ T cells in vitro, while high expression of IFNB1 was associated with chemotherapy resistance and a poor prognosis in glioblastoma." (PMID 35145511, 2021).
ovarian carcinoma (28 papers, 2012 to 2025). A malignant neoplasm originating from the surface ovarian epithelium. "We identified a series of necroptosis‐related genes involved in the pathogenesis of ovarian cancer, including STAT1, CASP8, and IFNB1, and provided a preliminary analysis of their interactions." (PMID 37681751, 2023).
psoriasis (28 papers, 2014 to 2025). An autoimmune condition characterized by red, well-delineated plaques with silvery scales that are usually on the extensor surfaces and scalp. "In contrast, type I IFNs IFNA2 and IFNB1 expression was greatly increased in paradoxical psoriasis relative to chronic plaque psoriasis." (PMID 29295985, 2018).